ICAM1 (intercellular adhesion molecule 1)
Diseases named in the same sentence as ICAM1 in open-access papers (continued):
Sharing a sentence is not in itself a finding about the gene and the disease.
tumor (continued). "In contrast, although ICAM-1 and TIMP-2 play relevant roles in tumor progression and extracellular matrix remodeling, the current literature does not provide direct evidence of their transcriptional regulation by miRNA-21." (PMID 41596621, 2026). "It further converts immature (CD101-) and mature (CD101+) neutrophils into a CD14+ICAM-1+ subset through STING-NF-κB-TNF-α signaling, enhancing tumor infiltration and antitumor activity." (PMID 41854362, 2026). "Pro-inflammatory cytokines up-regulate the expression of adhesion molecules, such as intercellular adhesion molecule-1 (ICAM-1) in various cell types, including endothelial, epithelial, immune, and tumor cells." (PMID 40142019, 2025). "Having observed Bevacizumab promotion of TNF-α induction of expression of ICAM-1 and VCAM-1 on the surface of HUVECs above, next we looked at the signs of effective priming of T cells to cross the blood vessel wall into the tumour microenvironment." (PMID 40650058, 2025). "PAK1KO increased the expression of ICAM-1 by 7 times and of VCAM-1 by 10 times in tumour tissues, showing increased density of ICAM-1 and VCAM-1 staining." (PMID 40943273, 2025). "However, from a clinical perspective, free-form anti-ICAM1 antibodies may interfere with multiple intercellular interactions during tumor development and metastasis, potentially impairing normal immune functions that depend on the interaction between LFA-1/Mac-1 and ICAM-1." (PMID 40528159, 2025). "The IHC results revealed a positive correlation between the expression levels of ICAM‐1 and the TNM stage of the tumor." (PMID 39996528, 2025). "Quantitative analysis of the tumor mass revealed that combination therapy with ICAM‐1–Dxd and B7‐H3‐CD3 led to a reduction in TNBC tumor growth compared with that in the control group." (PMID 39996528, 2025). "Metastatic tumor cells also secrete IL‐23, which induces TNF‐α production in LSECs, upregulating MMP9 and ICAM1 expression and promoting the formation of endothelial cell gaps." (PMID 40027151, 2025). "Adenosine reduces the expression of T-cell adhesion molecules (e.g., ICAM-1, VCAM-1), limiting the homing of effector T cells to tumor tissue while inhibiting the antitumor activity of NK cells and macrophages." (PMID 41415289, 2025). "DNAM-1 synergizes with other NK cell receptor ligands [including intercellular adhesion molecule-1 (ICAM-1), NKG2D-L, and CD48] to recognize CD155, thereby inducing NK cell cytotoxic responses that inhibit viral replication and control tumor burden." (PMID 40463500, 2025). "Oxygenation facilitates the expression of adhesion molecules like ICAM-1 and VCAM-1 on endothelial cells, enabling effective interactions between T cells and the tumor vasculature." (PMID 41048631, 2025). "Increased expression of endothelial adhesion molecules, intercellular adhesion molecule 1 (ICAM-1), and vascular cell adhesion molecule 1 (VCAM-1) stimulates intra-tumoral lymphocytes infiltration and thus promotes anti-tumour immunity." (PMID 40943273, 2025). "We used flow cytometry (FCM) sorting to isolate primary ICAM1+ MDMs and GPNMB+ MDMs from the tumor samples of GBM patients." (PMID 41174767, 2025). "ICAM-1 was expressed in 0.3% of CD3+ T cells overall, and in tumour and stromal compartments in 0.5% (range 0.0–61.1%) and 0.3% (range 0.0–50.4%) of CD3+ T cells respectively." (PMID 39792888, 2025). "Emerging targets, including Trop-2, B7-H3, ICAM-1, and GPRC5D, show restricted normal tissue expression and broad tumor prevalence, making them promising candidates for next-generation BsAbs." (PMID 41476945, 2025). "For example, it can normalize tumor vasculature, improve oxygenation, and upregulate ICAM-1 and VCAM-1, facilitating CAR cell entry into the tumor." (PMID 40722155, 2025). "An upregulation of ICAM-1 and VCAM-1 in the tumor following treatment appeared to be responsible for this phenotype." (PMID 40071851, 2025).
tumor (continued). "This activation subsequently enhances the expression of intercellular adhesion molecule 1 (ICAM1) in PDAC cells, which facilitates the adhesion and transendothelial migration of ECs in tumor tissues by forming an ICAM1-fibrinogen-ICAM1 bridge." (PMID 39974277, 2025). "The adhesion molecules VCAM1 and ICAM1 guide immune cell transmigration, with ICAM1 favoring neutrophils, macrophages, and lymphocytes, while VCAM1 primarily recruits monocytes and lymphocytes, ultimately regulating the tumor immune microenvironment." (PMID 40652770, 2025). "For instance, layilin, a membrane glycoprotein expressed by certain tumor-specific CTLs, enhances LFA-1 activation by stabilizing its interaction with ICAM-1." (PMID 39911389, 2025). "These myCAFs exhibited strong interactions with cytotoxic T/NK cells through the ICAM1, CD55, CXCL13, and CXCL16 signaling pathways, suggesting a potential contribution to tumor regression." (PMID 40107247, 2025). "This process upregulates cell adhesion molecules (ICAM-1 and VCAM-1), the death receptor Fas, and MHC I and II, thereby enhancing the recruitment and activation of innate immune cells and tumor-specific lymphocytes." (PMID 39941843, 2025). "For the outcome tumor recurrence, both VCAM-1 and ICAM-1 showed good performance in tumor tissue, AUC= 0.838 with cutoff point of 0.746 and AUC=0.835 with cutoff point of 0.708 respectively." (PMID 40652770, 2025). "For metastasis and colonization, EVs alter recipient cell behavior and prepare distant sites for tumor colonization by carrying molecules such as TGF-β receptors and ICAM1, inducing EMT and enhancing metastatic potential." (PMID 40103824, 2025). "A larger cohort and potential future experiments with autologous leukocytes will allow to investigate specific actions of LA toward the interplay of ICAM‐1 expression, TAM polarization and tumor survival." (PMID 41028965, 2025). "In tumor tissue, VCAM-1 and ICAM-1 demonstrated acceptable predictive performance, Area Under the Curve (AUC)=0.600 with cutoff point of 0.553 and AUC=0.664 with cutoff point of 0.475." (PMID 40652770, 2025). "To ascertain the clinical relevance of ICAM‐1 expression in TNBC tissues, we conducted IHC staining for ICAM‐1 on a series of 40 human TNBC tumor tissue samples and compared them with 40 normal mammary tissue samples." (PMID 39996528, 2025). "For example, Coxsackievirus CVA21 infects tumor cells by binding to intercellular adhesion molecule-1 (ICAM-1) and decay-accelerating factor, both of which are overexpressed on tumor cells." (PMID 40725148, 2025). "In our study, preoperative blood and tumor levels of VCAM-1 and ICAM-1 were lower in high SCS patients compared to low-medium SCS cases, while VCAM-1 levels in ascitic fluid were elevated in high SCS patients." (PMID 40652770, 2025). "Exosomes can be engineered to display ligands, such as ICAM-1 or LFA-1, which facilitate the recruitment of T cells by enhancing the adhesion and promoting immune cell trafficking to tumor sites." (PMID 40843170, 2025). "We stained the tumor tissue sections with five markers, α-SMA, GLUT1, CD68, ICAM1, and GPNMB, to exclude the possibility of simultaneous expression of ICAM1 and GPNMB by the same MDMs." (PMID 41174767, 2025). "In tumor tissues, both VCAM-1 and ICAM-1 levels were significantly elevated in the recurrence group." (PMID 40652770, 2025). "In preclinical models, the potent cytolytic activity of CVA21 against numerous tumor cells that express ICAM-1 and DAF, and the capability to induce immunogenic cell death that can initiate systemic anti-tumor immune responses, have been shown." (PMID 41313526, 2025). "Neutrophil-monocyte interactions involved ICAM1-(ITGAV+ITGB2) pairing, with dysregulation promoting pro-tumor TAM differentiation." (PMID 40948800, 2025). "Pomalidomide also reverses EBV- and KSHV-mediated immune evasion by restoring the expression of MHC I, ICAM-1, and CD86 on tumor cells." (PMID 40647389, 2025).
tumor (continued). "The flow chamber method evaluates the adhesion of cells to certain molecules, such as Intercellular adhesion molecule 1 (ICAM-1) and vascular cell adhesion molecule 1(V-CAM 1), involved in tumor progression." (PMID 39926108, 2025). "Neutrophils are innate immune cells in TME, which present two phenotypes: the (i) N1 (anti-tumor phenotype) that produces reactive oxygen species (ROS), tumor necrosis factor-α(TNF-α), and intercellular adhesion molecule 1 (ICAM-1)." (PMID 41369383, 2025). "Our tracking of MSC marker expression revealed progressive CD34 upregulation alongside declining ALCAM, CD44, and ICAM1 levels, indicating complex transcriptional reprogramming during MSC-to-tumor cell transitions." (PMID 40959090, 2025). "For this purpose, we covalently coupled ICAM‐1 mAbs with Cy5.5 (ICAM‐1–Cy5.5) and then intravenously injected ICAM‐1–Cy5.5 into 4T1 tumor‐bearing mice at a dosage of 5 mg kg−1." (PMID 39996528, 2025). "Compared with PBS, B7‐H3‐CD3 (5 mg kg−1), or ICAM‐1–Dxd (5 mg kg−1), the combination of ICAM‐1–Dxd and B7‐H3‐CD3 resulted in significant and sustained inhibition of tumor growth in tumor‐bearing model mice." (PMID 39996528, 2025). "Tumor-derived exosomal CMTM4 induces M2 macrophage polarization and immune suppression via NF-κB-mediated cytokine and ICAM1 upregulation, promoting metastasis; CMTM4 depletion enhances anti-PD-1 sensitivity." (PMID 41280929, 2025). "ICAM1 is an essential mediator in macrophage-HNSCC interaction and closely related to tumor cell stemness, invasiveness and chemoresistance." (PMID 40821990, 2025). "Despite the reduction in vascular density, PAK1KD enhanced the vascular normalisation by increasing the α-SMA/CD31 ratio and increased stromal ICAM-1 expression, which is suggestive of stromal or endothelial activation in PAK1KD tumours." (PMID 41294859, 2025). "ICAM-1 expression has been shown to be upregulated in patients with PTC and correlates with tumor aggressiveness." (PMID 40230479, 2025). "Compared with other treatments, combination therapy with ICAM‐1–Dxd and B7‐H3‐CD3 significantly elevated the concentrations of tumor‐suppressive cytokines, including TNF‐α, IL‐6, and IFN‐γ, to a greater extent." (PMID 39996528, 2025). "For instance, exosomes derived from dendritic cells or macrophages can be engineered to express ligands that target receptors overexpressed on tumor cells, such as LFA-1 or ICAM-1, further improving the specificity of drug delivery." (PMID 40843170, 2025). "In tumour tissues, PAK1KO increased the expression of ICAM-1 and VCAM-1 by approximately fourfold and fiftyfold, respectively." (PMID 41228228, 2025). "SASP molecules, like tumor necrosis factor alpha (TNFα) and intercellular adhesion molecule 1 (ICAM-1), promote the infiltration of natural killer (NK) cells into the tumor, where they execute their cytotoxic functions." (PMID 40723291, 2025). "By examining ICAM-1 levels in CD8+ T cells from the spleens and tumors of MC38 tumor-engrafted mice, we found that CD3+ or CD8+ T cells from tumors comprised a greater proportion of the ICAM-1+ population than did those from the spleens." (PMID 38169608, 2024). "The combination of ipilimumab and bevacizumab induces the expression of E-selectin, ICAM-1, and VCAM-1 on tumor endothelial cells and the adhesion of activated T cells to tumor endothelial cells." (PMID 39325128, 2024). "Amongst the up-regulated genes, we identified factors known to foster anti-tumor immunity such as CXCL11 (log2 = 2.2), IL-10 (log2 = 2.3), and ICAM-1 (log2 = 1.3)." (PMID 38228372, 2024). "In functional experiments in a tumour cell-endothelial cell interaction adherence model, adhesion was consistently affected, indicating that CXCL8 also upregulated ICAM1, promoting adhesion between tumour cells and endothelial cells." (PMID 39025845, 2024).
tumor (continued). "Treatment with an agonist of CD137 (expressed on tumor endothelial cells) monoclonal antibody increases the expression of ICAM-1, VCAM-1, and E-selectin on tumor endothelial cell surface promoting CD8+ T cells recruitment." (PMID 39325128, 2024). "Re-expression of WT ICAM-1 in ICAM-1 knockdown cells efficiently suppressed cell apoptosis and rescued tumor growth in mice." (PMID 39168965, 2024). "VEGF has been shown to impair leukocyte‐endothelial interactions by reducing the adhesion molecules, ICAM‐1, VCAM‐1, and LFA‐1, in angiogenic vessels and hampering the infiltration of T‐effector cells into tumours." (PMID 38602256, 2024). "Inhibiting ICAM1 significantly suppressed MAPK pathway activation, decreased MMP9 expression, and resulted in notable tumor shrinkage." (PMID 38907234, 2024). "Both LFA-1/ICAM-1 and VLA-4/VCAM-1 interactions are critical for the extravasation and infiltration of recruited NK cells to the tumor." (PMID 38671750, 2024). "The transmembrane glycoprotein receptor intercellular adhesion molecule 1 (ICAM-1) is expressed at low levels in multiple cell types, including endothelial cells, immune cells, and tumor cells." (PMID 39596815, 2024). "Combination of sunitinib and anti-CD40 monoclonal antibody treatment increases the expression of ICAM-1 and VCAM-1 on tumor endothelial cells, enhancing intratumoral infiltration of CD8+ cytotoxic T cells." (PMID 39325128, 2024). "As controls, tumor‐bearing mice were treated with PBS, ICAM1 antibody alone or paclitaxel as controls at same dosage and time interval." (PMID 38874532, 2024). "The proteins CAPS3, ICAM-1, CXCR4, and PTGS2 are key players in regulating the life cycles of tumor cells." (PMID 38502348, 2024). "The tumor cells from the rapamycin-treated mice expressed higher levels of CD40, CD80, and ICAM-1 than those from the control mice." (PMID 38791040, 2024). "Even so, ICAM-1 and VCAM-1 expression is a double-edged sword for tumor cells because the innate immune system can prevent tumor cells from spreading though physical contact-mediated mechanisms." (PMID 38786066, 2024). "Additionally, the G. frondosa extract demonstrated inhibition of ICAM-1 (Intercellular Adhesion Molecule 1) expression in vascular endothelial cells, suggesting that its mechanism of action involved blocking the adhesion of tumor cells to lung tissue, thereby inhibiting metastasis." (PMID 38545465, 2024). "Its activation upregulates the expression of ICAM-1 and VCAM-1 on endothelial cells and reprograms tumor vasculature." (PMID 39325128, 2024). "STING activation synergizes with VEGF receptor 2 (VEGFR-2) blockade, leading to normalization of the tumor vasculature, upregulation of VCAM-1 and ICAM-1, and regression of immunotherapy-resistant tumors." (PMID 39035739, 2024). "In this regard, IFNγ produced by CAR-T cells upregulates ICAM-1 on tumor cells and strengthens CAR-T and tumor cell interaction, facilitating tumor killing in solid tumors." (PMID 38779672, 2024). "Our study revealed that statins effectively suppressed ICAM1 expression and counteracted the activation of the MAPK pathway downstream of tumor cells by neutrophils." (PMID 38907234, 2024). "Transcriptomic sequencing combined with human and murine functional experiments revealed that neutrophils, through direct CD11b-ICAM1 interactions, activated the MAPK signaling pathway in TNBC cells, thereby enhancing tumor cell invasion and migration." (PMID 38907234, 2024). "N1-TANs, induced by IFN-γ, enhance tumor cytotoxicity and attenuate immunosuppression by producing TNF-α, intercellular adhesion molecule-1 (ICAM-1), ROS, and apoptosis-related factor (Fas)." (PMID 39877377, 2024). "The simultaneous upregulation of tumour sEV PD-L1, MHC-I and ICAM-1 by both IFN-γ and aT-sEVs indicates intensive immunosuppression since it has been proven that coexpressed MHC-I and ICAM-1 would cooperate with sEV PD-L1 to strongly suppress CD8+ T cells." (PMID 38719909, 2024).
tumor (continued). "As a result, blocking PD-1 and CD80 on aT-sEVs nearly abrogated their function in regulating tumour cell membrane PD-L1, MHC-I and ICAM-1." (PMID 38719909, 2024). "Nitric oxide (NO) affects leukocyte recruitment reducing tumor endothelial cell expression of adhesion molecules (E-selectin, VCAM-1, and ICAM-1) and pro-inflammatory cytokines." (PMID 39325128, 2024). "In preclinical studies, CAR-T cells constructed with antigens such as TSHR, ICAM-1, GFRα4, B7-H3, and CEA demonstrated anti-tumor effects." (PMID 38911868, 2024). "Abolishing ICAM-1–FGG interaction induces NSCLC cell death by activating caspase-9/3 and significantly inhibits tumor development in a mouse xenograft model." (PMID 39168965, 2024). "Correlatively, the terminal tumor weights were determined as 0.83±0.56g (PBS), 0.84±0.47g (ICAM1 mab), 0.61±0.19g (paclitaxel), 0.16±0.07g (I1‐MMAE) and 0.08±0.02g (I1‐DXd), respectively." (PMID 38874532, 2024). "Immune-related proteins were first analysed, and we revealed that IFN-γ increased not only tumour cell PD-L1 but also antigen peptide transporter 1 (TAP1), HLA-A, HLA-B, HLA-C and ICAM-1, indicating strong adhesion and enhanced immunogenicity." (PMID 38719909, 2024). "The significant upregulation of ICAM1-AREG elucidates the promotive effects of VCAN+ TAMs on angiogenesis and tumor development." (PMID 39232806, 2024). "Acetylation of histone H3 has been well characterized in tumor ECs, which epigenetically regulates the expression of key genes essential for EC function and angiogenesis, including CLU, FBN1, TSPAN2, and ICAM1." (PMID 38580870, 2024). "We identified surface ICAM-1 on CD8+ T cells as a novel biomarker of T-cell activation, proliferation, tumor infiltration, and antitumor effector function." (PMID 38169608, 2024). "Through the deregulation of ICAM-1 and vascular cell adhesion protein 1 (VCAM-1), VEGF-A can also lessen the adhesion between lymphocytes and tumor vascular endothelial cells, which in turn reduces TIL penetration." (PMID 37298230, 2023). "In tumor progression, aberrant ICAM-1 expression and impaired LFA-1/ICAM-1 function has been observed." (PMID 36895477, 2023). "CAMs, including ICAM-1 and VCAM1, are involved in the interaction and recruitment of immune cells to tumor sites." (PMID 37627528, 2023). "ECs downregulated ICAM-1 and E-selectin due to tumor VEGF production, while the chemokines secreted from tumor cells still attracted T cells." (PMID 37064144, 2023). "VEGF-A inhibits the release of inter-endothelial and vascular cell adhesion molecules (ICAM-1, VCAM-1) and hinders the migration of CART cells across the vascular endothelial cell barrier into the tumor tissue." (PMID 37623511, 2023). "The expression of tumor-promoting cytokines, chemokines, and growth factors, such as IL-6, IL-11, and IL-23, CCL2, CCL5, CXCL7, CXCL5, intercellular adhesion molecule-1 (ICAM1), and TGF-, is inhibited by NT157, according to studies, which prevents TAMs." (PMID 37175871, 2023). "Depletion of ICAM1, CD8+ T cells, or NK cells significantly increased tumor growth and shortened the survival time." (PMID 36871040, 2023). "For instance, F. nucleatum has been shown to enhance the adhesion of CRC cells to endothelia cells, and in this way, promotes tumour progression and metastasis through upregulation of ALPK1 and ICAM1 expression." (PMID 36944721, 2023). "However, despite also observing higher mRNA expression in the presence of lymphocytic infiltration, we could not associate ICAM1 with any characteristic of tumor aggressiveness or patient outcome." (PMID 36906717, 2023). "(D) Heatmaps showing expression of ICAM1 and ICAM-1 cleavage related proteases MMP9, ELANE, CTSG, ADAM10, and ADAM17 in normal or tumor tissue of 22 different cancer types." (PMID 37732732, 2023).